CTLA4 (cytotoxic T-lymphocyte associated protein 4)
Diseases named in the same sentence as CTLA4 in open-access papers (continued):
Sharing a sentence is not in itself a finding about the gene and the disease.
metastatic disease (72 papers, 2012 to 2025). "Checkpoint inhibitor immunotherapies targeting programmed cell death protein 1 (PD-1) or cytotoxic T-lymphocyte-associated protein 4 (CTLA-4) have been shown to significantly improve the overall survival of patients with advanced stage metastatic disease." (PMID 35810563, 2022). "Currently, only pembrolizumab can be considered as adjuvant therapy for intermediate- or high-risk operable RCC [I, C], while the metastatic disease is managed with tyrosine-kinase inhibitors (TKIs) or TKIs in combination with a PD-L1/CTLA-4 blockade." (PMID 36499030, 2022). "The latest research on metastatic tumor anti-CTLA-4 therapy shows a high risk of developing irAEs; the most remarkable irAEs include cutaneous diseases, like rash and pruritus, along with gastrointestinal tract irAEs, such as colitis." (PMID 34367975, 2021). "Currently, the use of monoclonal antibodies targeting cytotoxic T-lymphocyte-associated antigen-4 (CTLA-4), PD-1, and Program Cell Death Ligand 1 (PD-L1) has remained limited to unresectable, locally advanced and metastatic disease." (PMID 32500025, 2020). "CTLA-4 expression was significantly correlated with primary metastatic diseases and associated with a a reduced OS and CSS in the whole cohort, as well as in a ccRCC-only subgroup." (PMID 31137694, 2019). "Though associated with primary metastatic diseases, CTLA-4 expression in a non-metastatic disease subgroup is still significantly associated with a worse OS and CSS." (PMID 31137694, 2019). "Immunotherapy targeting the programmed cell death protein 1/programmed cell death ligand 1 (PD1/PD-L1) and cytotoxic T-lymphocyte-associated protein 4 (CTLA-4) immune checkpoint signaling has proven to be successful in the treatment of various metastatic tumors." (PMID 41227363, 2025). "Systemic administration of immune checkpoint inhibitors targeting programmed cell death protein 1 (PD1)/programmed cell death 1 ligand 1 (PD-L1) and cytotoxic T lymphocyte associated protein 4 (CTLA4) co-inhibitory pathway improves overall survival in patients with metastatic tumors." (PMID 39534532, 2024). "In RCC, the blockade of PD-1 and CTLA-4 has become the new treatment approach in patients with intermediate- and high-risk metastatic tumors, whereas monotherapy with the PD-1 inhibitor nivolumab is the second-line or third-line treatment approach after failure of VEGF tyrosine kinase inhibitors." (PMID 34912710, 2021). "The prognosis for both locally advanced and metastatic tumours is significantly improved by inhibiting immunological checkpoints that suppress antitumoral immune responses, such as programmed cell death (PD-1), its ligand PD-L1, or cytotoxic T-lymphocyte-associated protein 4 (CTLA-4)." (PMID 37189436, 2023). "In recent years, immune checkpoint inhibitors targeting cytotoxic T-lymphocyte-associated antigen 4 (CTLA-4), programmed death (PD)-1, and PD-ligand 1 (PD-L1) have demonstrated durable responses in subsets of patients with metastatic disease." (PMID 40837578, 2025). "ICIs, such as pembrolizumab, nivolumab, and atezolizumab, enhance immune responses against tumors by targeting PD-1, PD-L1, and CTLA-4 and offer an important option for treating cancer, particularly for advanced or metastatic disease." (PMID 40673965, 2025). "Despite advances in targeted therapies (e.g., BRAF/MEK inhibitors) and immunotherapies (e.g., anti-PD-1/PD-L1/CTLA-4), clinical outcomes remain variable, particularly in metastatic disease, where 5-year survival rates drop below 30%." (PMID 40821828, 2025). "Clinical significance of these approaches can further be tested both in-vitro and in-vivo in combination with already established immunotherapeutic agents, such as PD1/PDL1/CTLA4 blocking antibodies, commonly used for the treatment of metastatic disease." (PMID 39742254, 2024). "Another study indicated that inhibition of MMP-2/MMP-9 improves the efficacy of PD-1 or CTLA4 blockade in the treatment of primary and metastatic tumors." (PMID 35178444, 2022).
metastatic disease (continued). "TIM-3 and TIGIT were significantly expressed on CD4eff in metastatic tumors compared with the other tissue types, whereas PD-1 and CTLA-4 expressions were significantly lower in PBMC." (PMID 35320356, 2022). "Immune inhibitors like PD-1, BTLA and CTLA-4 were significantly highly expressed in metastatic tumors with reduced neoantigens, which further supported that reduction of neoantigens was associated with functional deficiency of immune cells." (PMID 33995666, 2021). "Noteworthy, when an anti-CTLA-4 mAb is administered to patients with metastatic tumors, irAEs always occur." (PMID 34367975, 2021). "A total of 71 patients with mUM who received 75 lines of anti-PD1/L1 ± anti-CTLA4 ICI for metastatic disease at our institution were identified." (PMID 34298857, 2021). "The combination of BEMPEG and anti-CTLA-4 with primary tumor RT or resection enabled effective control of local and metastatic disease in a preclinical murine NSCLC model." (PMID 33937052, 2021). "Both PDCD1 (gene for PD-1) and CTLA4 are decreased in the recurrent/metastatic tumor compared to the primary tumor." (PMID 33796222, 2021). "The addition of BEMPEG and anti-CTLA-4 to local treatment prevented metastatic disease in the lungs as compared to local treatment alone (p<0.001)." (PMID 33937052, 2021). "Pre-clinically, SB-3CT treatment enhanced the therapeutic efficacy of PD-1 or CTLA-4 blockade in the treatment of both primary and metastatic tumors." (PMID 32988398, 2020). "SB-3CT treatment enhanced the therapeutic efficacy of PD-1 or CTLA-4 blockade in the treatment of both primary and metastatic tumors, thus providing a novel therapeutic strategy for SB-3CT and ICB therapy to enhance immunotherapy efficacy." (PMID 32988398, 2020). "These immune responses amplified by the CTLA‐4 inhibitor led to a notable systemic therapeutic outcome to effectively suppress the growth of primary and metastatic tumors." (PMID 31763151, 2019). "In our study, high levels of FOXP3+ and CTLA-4+ T cells were documented in metastatic tumours in the ALNs and were higher than the levels in the corresponding primary tumours." (PMID 29390966, 2018). "In our study, when compared to mice treated only with anti-CTLA-4 or lycorine hydrochloride therapy, mice on the combination treatment regimen showed significantly reduced orthotopic and metastatic tumors." (PMID 28416753, 2017). "Herein, for the first time, we report that lycorine hydrochloride in combination with anti-mouse CTLA-4 inhibited orthotopic and metastatic tumors by downregulating Tregs, which was accompanied with upregulation of effector T cells." (PMID 28416753, 2017). "To determine the immunomodulatory potential of lycorine in RCC, we evaluated anti-tumor effects of lycorine hydrochloride alone or in combination with anti-mouse CTLA-4 in an orthotopic and metastatic tumor mice model." (PMID 28416753, 2017). "The price of potential long-term survival to metastatic tumors is an atypical immune toxicity, reflecting the mechanism of action of anti-CTLA-4 antibodies." (PMID 26337719, 2015). "The potential price of a long-term cure of metastatic tumors is atypical immune toxicity, reflecting the immune mechanism of action of anti-CTLA-4 antibodies." (PMID 26337719, 2015). "Patient 5 (V600EBRAF) presented with extensive metastatic disease and was enrolled in the CheckMate 067 trial (anti-PD-1 antibody nivolumab alone versus anti-CTLA-4 antibody ipilimumab alone versus combination of the two)." (PMID 26095797, 2015). "Regarding CTLA4, it is well known that it is the second target of checkpoint inhibition therapeutic approaches in RCC, and CTLA4 expression was significantly correlated with metastatic diseases and associated with a reduced survival in ccRCC." (PMID 38067341, 2023). "Therefore, additional pharmacological intervention to prevent or treat these adverse events should be considered when standardizing the combination of anti-PD-1 and anti-CTLA-4 in metastatic tumors." (PMID 36778017, 2023).
metastatic disease (continued). "The CTLA-4 expression in TIMC is associated with primary metastatic diseases (p = 0.006, not significant with Bonferroni correction correlation coefficient 0.153)." (PMID 31137694, 2019). "As we showed that the combination of PD-1 and CTLA-4 expression is correlated to metastatic diseases, we hypothesize that the expression of these checkpoint molecules may be an early marker for micro metastatic diseases undetectable by cross-sectional imaging." (PMID 31137694, 2019). "This study highlights that immunotherapy, particularly anti-PD1 plus anti-CTLA4 combination, may provide cure even for patients with metastatic disease, consistently with the plateau of PFS curves in clinical trials with dual checkpoint inhibition (2-year PFS of about 70%)." (PMID 34200267, 2021). "However, the addition of anti-PD-L1 antibody to CTLA-4- improved the response to metastatic tumors." (PMID 29253865, 2017). "All mice treated with RT or surgical resection of primary tumor alone succumbed to metastatic disease, and all mice treated with BEMPEG and/or anti-CTLA-4 succumbed to primary tumor local progression." (PMID 33937052, 2021). "The median values of CTLA4+, ICOS+, and GITR+ TILs in the primary tumor were significantly higher than those in the metastatic tumor." (PMID 29614981, 2018). "The authors have used a clinically relevant pre-clinical model of metastatic tumor and have shown that the combination therapy of NDV and CTLA-4 checkpoint blockade controlled both local and distant tumors better than either anti-CTLA-4 or NDV treatment alone." (PMID 26580645, 2015). "Combined treatment with anti-CTLA-4 antibody and tumor lysate-pulsed dendritic cells in mice with OS lead to decreased Tregs and increased CD8 T cells in metastatic tumor leading to decreased metastasis and increased EFS." (PMID 26286851, 2015). "In treatment with anti-PD-1 inhibitors, with or without CTLA-4 inhibitors, the incidence of late-onset irAEs (>1 year) is higher in patients treated for metastatic disease." (PMID 35911362, 2022). "Similarly, with only primary tumor control, mice succumb to metastatic disease unless combined with BEMPEG and anti-CTLA-4." (PMID 33937052, 2021). "In a spontaneously metastasizing immunologically “cold” model of early-stage NSCLC, we report that the combination of anti-CTLA-4 and BEMPEG inhibits the development of distant metastases and effectively eradicates IV injected tumor cells representing micro-metastatic disease." (PMID 33937052, 2021). "The mice treated with anti-CTLA-4 and BEMPEG were euthanized due to primary tumor burden, while most mice receiving only local treatment of the primary tumor with RT or surgery died from metastatic disease." (PMID 33937052, 2021). "Note that anti-CTLA-4 and BEMPEG treatments were investigated separately and in combination in a preliminary experiment and did not appear to have a significant impact on tumor growth; however, the treatment combination of anti-CTLA-4 and BEMPEG did result in less metastatic disease." (PMID 33937052, 2021). "We thus sought to determine the relative efficacy of combination GVAX/anti-CTLA-4 therapy in models of metastatic disease, both in the presence and absence of primary tumor." (PMID 23557194, 2013). "However, analysis of a mono anti-CTLA-4-treated patient cohort was not possible due to its current limited use as a monotherapeutic agent in metastatic disease." (PMID 37525015, 2023). "Therefore, CM@M‐MON@Ce6‐mediated PDT and magnetic hyperthermia combined with anti‐CTLA‐4 suppressed the growth of not only primary tumors but also metastatic tumors with no noticeable systemic toxicity." (PMID 31763151, 2019). "Although the expression of CTLA-4 has been remarkably different among primary CRC, non-tumoral samples, recurrent tumors, and metastatic tumors." (PMID 34067631, 2021).
metastatic disease (continued). "CTLA-4 expression was significantly different in primary CRC, non-tumoral samples, recurrent tumors, and metastatic tumors (N = 736; metastatic = 1 sample, recurrent tumor = 2 samples, primary tumor = 632 samples, and solid tissue normal = 101 samples, p = 2.1 × 10−7)." (PMID 34067631, 2021).
COVID-19 (71 papers, 2020 to 2026). A disease caused by infection with severe acute respiratory syndrome coronavirus 2. "Overexpression of CTLA4 has been associated with a more severe disease course in patients with COVID-19, but there have only been a few reports on the disease course of COVID-19 in patients with CTLA4 haploinsufficiency." (PMID 37260564, 2023). "Investigators have reported that CD4 and CD8 T cells from patients with COVID-19 had expression of multiple inhibitory molecules including PD-1, PD-L1, Tim-3, and CTLA-4, indicative of T cell exhaustion." (PMID 39903535, 2025). "This reduction, coupled with increased expression of exhaustion markers (PDCD1, CTLA4), suggests that T cells in severe COVID-19 are overactivated and subsequently exhausted, impairing their ability to control the virus." (PMID 39928675, 2025). "Comparisons of the vaccine types after the COVID-19 vaccine among sera of participants groups according to CTLA-4 level." (PMID 38180994, 2024). "The diminished antibody response to the COVID-19 vaccines is attributed to the well-documented impact of the CTLA-4-Ig and TNF-α inhibitors on reducing the frequency of peripheral memory B cells in humans’ peripheral blood." (PMID 39456932, 2024). "We also found that DCs and monocytes were highly interactive with adaptive immune cells in both diseases, but that innate cells in COVID-19 appear to be more capable of immunosuppressive function through CTLA-4 and TIM-3-mediated interactions." (PMID 36992700, 2023). "This implies that the use of CTLA-4-based therapy can be an effective approach to managing patients with COVID-19." (PMID 36992283, 2023). "Asymptomatic COVID-19 patients, along with controls, were examined in a recent study for the expression levels of CTLA4 on the Tregs." (PMID 36992283, 2023). "Several studies have also confirmed the presence of immune checkpoint receptors, including CTLA-4, PD-1, and Tim-3 on the T cells of COVID-19 patients, often increasing as symptoms and disease severity progress." (PMID 36817450, 2023). "Regarding the comorbid group, a recent study showed that CTLA-4 gene expression is shared in five different comorbid groups during COVID-19, including DM and hypertension." (PMID 36297185, 2022). "Patients with severe vs. mild COVID-19 or control subjects were noted to have elevated levels of peripheral blood PD-1+ and CTLA-4+ cytotoxic T cells." (PMID 36146713, 2022). "The reduced antibody response to COVID-19 vaccine is likely due to the well-known effect of the CTLA-4-Ig and TNF-α inhibitors on the reduction of the frequency of MBCs in the human peripheral blood." (PMID 35309297, 2022). "A patient subset (8%) with the mild disease had high levels of checkpoint inhibitor CTLA-4 on T-cells, probably involved in the downregulation of immune activation during COVID-19-related cytokine storms." (PMID 36366522, 2022). "Particularly in severe COVID-19 patients, higher frequencies of SARS-CoV-2-specific IFN-γ+CD69+CD4+ T cells, with a high expression of Cytotoxic T-Lymphocyte-associated Protein 4 (CTLA-4), were observed as compared to uninfected and convalescent patients." (PMID 36499533, 2022). "Further, CTLA-4, has been proposed as a candidate molecule with potential for controlling inflammation in severe COVID-19 patients in the context of Treg based disease management in COVID-1946." (PMID 33986382, 2021). "CTLA4 is an inhibitory co-receptor that has been scored as one of the exhaustion markers on T cells and whose levels have been assessed in COVID-19 patients." (PMID 33986382, 2021). "Along these lines, CTLA-4 expression was significantly lower in convalescent patients with severe COVID-19 and markedly lower in patients with mild COVID-19." (PMID 33546489, 2021). "Among COVID-19 patients, we observed the trend of increased Treg-CTLA4 and CD4-GZMB, and decreased CD4-Naïve and CD4-GZMK in severe over non-severe groups." (PMID 35095917, 2021).